BBC3 (BCL2 binding component 3)
Diseases named in the same sentence as BBC3 in open-access papers (continued):
Sharing a sentence is not in itself a finding about the gene and the disease.
latent infection (1 paper, 2016). "The upregulation of transcripts of BBC3, GADD45A, MDM2, TP53I3, and downregulation of HEXIM1 during latent infection was confirmed as significant by RT-qPCR." (PMID 27898737, 2016).
retinal diseases (1 paper, 2022). "Apoptosis is also a characteristic hallmark of retinal diseases, so BBC3 and BCL2L13, RARA were investigated, as well as genes (EFEMP1, CFH) involved in the regulation of methylation sites." (PMID 36078063, 2022).
status epilepticus (1 paper, 2013). Status epilepticus is defined as a continuous seizure lasting more than 30 min, or two or more seizures without full recovery of consciousness between any of them.
T-cell acute lymphoblastic leukemia (1 paper, 2025). Acute lymphoblastic leukemia of T-cell origin. "Additionally, Hes1 directly inhibits the expression of the BBC3 gene (encoding the pro-apoptotic factor PUMA) in T-cell acute lymphoblastic leukemia (T-ALL), thereby suppressing oncogenic stress-induced apoptosis during T-cell transformation." (PMID 40755759, 2025).
thymic tumors (1 paper, 2023). "Consistent with the oncogenic role of AKT, FOXO target genes include tumor-suppressive genes (BCL2L11(Bim), BBC3(PUMA), CDKN1B(p27Kip)), and overexpression of FOXOs induces apoptosis and cell cycle arrest, while suppression of FOXOs promotes tumorigenesis in prostate, gastric, and thymic tumors." (PMID 37773170, 2023).
type 2 diabetes (1 paper, 2015). "Islets isolated from organ donors with type 2 diabetes had elevated mRNA expression of the pro-apoptotic BH3-only molecules BIM (BCL2L11) and PUMA (BBC3), highlighting that their activation is cell type and stimulus-specific." (PMID 26137578, 2015).
ZIKV infection (1 paper, 2017). "One recent study reported that several apoptotic regulators, including ZMAT3, PMAIP1, TNFRSF10D, BBC3, were upregulated, and cell cycle genes, such as E2F1 and E2F2, were downregulated after ZIKV infection." (PMID 29116029, 2017). "Two pro-apoptotic factors, TNFRSF10D and BBC3, were also upregulated about 2-fold at both gene and gene ISO levels by ZIKV infection." (PMID 29116029, 2017).
tumor (224 papers, 2006 to 2026). "As mere expression of the anti-apoptotic target proteins has not been clearly demonstrated to predict response to BH3-mimetic treatment, we investigated the expression of the recently suggested predictive biomarkers BCL2L12 and BBC3 for paediatric tumours." (PMID 38942989, 2024). "In contrast, BPA decreased the expression of BBC3, an important gene that promotes apoptosis, decreases tumour suppressor genes such as PTEN and also decreases MLH-1, which plays a role in DNA repair related to cell proliferation." (PMID 36235125, 2022). "In the present study, the MSI frequency of tumor-related genes, except BBC3 and MYC, was higher in B5-MSI tumors than in B5-MSS tumors, suggesting that the B5 panel is a powerful tool for defining the MSI status of CRC." (PMID 34563193, 2021). "Alternative splicing of pre-mRNA PUMA (also known as BBC3) yields four splice variants, PUMA-α, -β, -δ and -γ in normal and tumor cells following chemotherapeutic treatment." (PMID 26580598, 2015). "Since evading apoptosis is a crucial characteristic of tumor cells, the upregulation of BBC3 may counteract this tendency, making tumor cells more susceptible to apoptotic signals and leading to cell death." (PMID 41142795, 2025). "However, loss of the representative pro‐apoptosis members BAX, BIM and BBC3 is also a common trend in oncogenesis, facilitating tumour formation and progression through genomic deletion, silencing and mutation in several cancers." (PMID 32419250, 2020). "Functional studies have reported that miR-483-3p may act as an oncogene by targeting BBC3/PUMA directly or tumor suppressor via repression of multiple targets including CDC25A, BIRC5, and RAN." (PMID 29717264, 2018). "Research has demonstrated that BBC3 is significantly upregulated in DLBCL, suggesting that it promotes apoptosis in tumor cells, thereby inhibiting tumor growth and development." (PMID 41142795, 2025). "In xenograft models, BBC3 knockdown compromised the antitumor efficacy of AQB+CBPt, as evidenced by accelerated tumor growth and higher Ki-67 staining compared with controls." (PMID 41353219, 2025). "Several studies showed that metastatic NB cells display distinctive features from primary tumor cells, with upregulation of immunosuppressive molecules (HLA-G and calprotectin) and downmodulation of tumor suppressor genes (i.e., SIRT6, BBC3/PUMA, and CADM4)." (PMID 40508186, 2025). "Consistently, MBG3 and NB tumours of the INFORM cohort expressed BCL2L12 at comparatively low levels and BBC3 at above-average levels." (PMID 38942989, 2024).
tumor (continued). "Comparing the four canonical MB subgroups in detail, Group 3 tumours both expressed BCL2L1 (BCL-XL) and BBC3 at significantly higher levels than the other subgroups and showed significantly lower BCL2L12 expression than the MBSHH and MBWNT subgroups." (PMID 38942989, 2024). "The proapoptotic protein BBC3/PUMA is also eliminated via CMA, which resist the apoptosis of tumor cell." (PMID 37655052, 2023). "A decisive tumor‐suppressive role of FoxOs is present upon cellular damage, which results in FoxO‐mediated induction of pro‐apoptotic genes such as TNFSF10 (TRAIL), FASLG (FasL), BCL2L11 (BIM), or BBC3 (PUMA)." (PMID 39533662, 2025). "Several studies showed that NB metastatic cells express distinctive features from primary tumor cells, including down-regulation of several tumor suppressor genes (i.e., SIRT6, BBC3/PUMA, STK11, CADM4 and GLTSCR2) and up-regulation of immunosuppressive molecules, such as calprotectin and HLA-G." (PMID 33921337, 2021). "Additionally, previous reports have suggested that the tumor suppressive potential of YAP1 is due to its binding to TP73 and its regulation by RASSF1A leading to the expression of pro-apoptotic genes like BBC3/PUMA and BAX." (PMID 30744076, 2019). "Previous reports have suggested that the tumor suppressive potential of YAP1 is due to its binding to TP73 and its regulation by RASSF1A leading to the expression of pro-apoptotic genes like BBC3/PUMA and BAX." (PMID 29179447, 2017). "In addition, we found that several miR-125b target genes were down regulated and two of these BBC3 (PUMA) and Neu1 are known tumor suppressors." (PMID 25184537, 2014). "Therefore, our microarray analysis results fit well with the known effects of signaling pathways and genes on tumorigenesis, suggesting that the promotion of tumor development by C1QTNF6 might be mediated through regulation of Acute Phase Response signaling and ID1, BBC3, and DDIT3 gene expression." (PMID 34906149, 2021). "Thus far, two of these target genes, BBC3 and NEU1, that are tumor suppressor genes but not yet studied in PDAC, appear to be functional targets of miR-125b since knockdown of miR125b caused their up regulation." (PMID 25184537, 2014). "Moreover, RNA-seq data from each of 40 advanced PDAC tumor specimens from the TCGA data base indicate a negative correlation between expression of miRNA-125b and five of six potential target genes (BAP1, BBC3, NEU1, BCL2, STARD13)." (PMID 25184537, 2014).
cancer (217 papers, 2007 to 2025). A tumor composed of atypical neoplastic, often pleomorphic cells that invade other tissues. "TEL oncogene was shown as TF of CDKN1A and BBC3 and is related to “transcriptional misregulation in cancer” pathway." (PMID 30706161, 2019). "Inhibition or deletion of BBC3 impairs apoptosis and contributing to the development of cancer and chemo-resistance." (PMID 30042885, 2018). "IPA analysis of these unique up-regulated genes indicated that some genes were associated with cell transformation during cancer progression (ABL1, TRIO, FOSB, NRCAM, TRIB2 and CDK6) and others with cell survival (e.g., BCL10, BBC3, FGF8, HSPA4 and SOD1)." (PMID 29137349, 2017). "Most genes related to signal transduction in the cytoplasm were inactivated in the pathway of the Molecular Mechanism of Cancer; however, the gene expression of NF-κB, c-FOS, c-JUN, MDM2, AURORA-A, BBC3, BIM, and p21CIP1 was significantly increased." (PMID 35328637, 2022). "The quantitative PCR analysis displayed the fold changes of three related genes (GADD45B, SENS2 and BBC3) for MD12a and compound 3, which were applied to HepG2 and MCF-7 cancer cells." (PMID 34830055, 2021). "Specifically, we analyzed the role of five lncRNAs (BBC3, STK11IP, XIST, FDFT1, and PRR14), which are known to be related to cell growth and apoptosis in cancer development." (PMID 34295808, 2021). "In unstressed cancer cells TRIM28 represses the expression of pro-apoptotic genes: TP53AIP1, BAX, BBC3 (PUMA) and PMAIP1 (NOXA), further suggesting that TRIM28 provides survival advantage to cancer cells." (PMID 28851455, 2017). "Alterations of the regulatory function of ATF3 is highlighted by our finding that ATF3 is required for both activation and repression of pro-apoptotic genes such as BBC3/PUMA and TNFRSF10B/DR5 in stress response and cancer." (PMID 22046379, 2011). "This combination upregulates AIF, BBC3, PARP1, and Caspase‐3 genes in cancer cells to >25‐fold." (PMID 36241419, 2023). "Furthermore, BBC3 and DVL2 were involved in Hippo signaling pathways (shown in dark green color box) and cancer pathways (shown in orange color box)." (PMID 35237522, 2022). "BBC3/PUMA, BMF, BIM, and PMAIP1/NOXA are all more upregulated in cancer cells." (PMID 36195608, 2022). "CMA may aid cancer proliferation by the degradation of the inhibitors of cell proliferation, such as Rho-related GTP binding protein RhoE (RND3], and pro-apoptotic protein Bcl-2-binding component 3 (BBC3)." (PMID 35887082, 2022).
cancer (continued). "Using qPCR assay for known genes modulated NT157 in other cancer models, we identified that NT157 decreased expression of oncogenes BCL2, CCND1, MYB, and MYC and increased genes related to cellular stress and apoptosis, JUN, BBC3, CDKN1A, CDKN1B, FOS, and EGR1 (all p < 0.05)." (PMID 36224313, 2022). "Differential upregulation of BBC3/PUMA, BMF, BIM, and PMAIP1/NOXA between non-transformed and cancer cells was confirmed by RT-PCR." (PMID 36195608, 2022).
infection (26 papers, 2007 to 2026). The state of being infected such as from the introduction of a foreign agent such as serum, vaccine, antigenic substance or organism. "BBC3, encoding an essential pro-apoptotic protein, was up-regulated more than 32 times at 24 h post infection." (PMID 25344771, 2014). "Because BBC3as is induced early in infection, we reasoned that BBC3 is subject to active downregulation during the infection." (PMID 29089033, 2017). "Only in the BBC3as knockout cells was there a remarkable increase of sequencing coverage in the sense direction in the first, slowly processed half of the BBC3 gene upon infection." (PMID 29089033, 2017). "Interestingly, we also observed a slight induction of the BBC3 sense RNA immediately upon infection, as in the RT-qPCR and Nanostring experiments." (PMID 29089033, 2017). "The balanced upregulation of pro-apoptotic (FAS, BBC3) and anti-apoptotic (BCL2A1, TRAF1) genes in TIGR4-infected cells likely mitigates extensive cell death, enabling Spn to maintain host cell viability for sustained infection." (PMID 40475528, 2025). "However, the BBC3 mRNA synthesis showed a marked decrease upon infection in wild type, but not in BBC3as knockout cells." (PMID 29089033, 2017).
adenocarcinoma (3 papers, 2003 to 2022). A common cancer characterized by the presence of malignant glandular cells. "A slight downregulation of the MAP2K and BBC3 genes was also noted in both the adenocarcinoma arrays when compared to the normal squamous RNA gene expression pattern." (PMID 14583777, 2003).
BBC3 also shares sentences with these, for which no sentence is quoted: hepatocellular carcinoma (21 papers); glioma (19); neuroblastoma (19); leukemia (15); myeloma (10); non-small cell lung carcinoma (10); B-cell lymphoma (7); colitis (7); liver cancer (7); heart failure (6); ischemia (6); Cerebral ischemia (5); Parkinson disease (5); head and neck cancer (4); liver fibrosis (4); multiple myeloma (4); neurodegenerative disease (4); oral squamous cell carcinoma (4); renal carcinoma (4); sarcoma (4); steatosis (4); diabetes (3); liver disease (3); lung adenocarcinoma (3); acute myeloid leukemia (2); adenoma (2); anaemia (2); breast tumors (2); chronic lymphocytic leukemia (2); chronic myeloid leukemia (2).
A further 89 diseases each share a sentence with BBC3 in 2 papers or fewer.